STIP1 (stress induced phosphoprotein 1)
Diseases named in the same sentence as STIP1 in open-access papers (continued):
Sharing a sentence is not in itself a finding about the gene and the disease.
childhood asthma (1 paper, 2020). "We aimed to determine the associations between stress-induced phosphoprotein 1 (STIP1) and glucocorticoid-induced transcript 1 (GLCCI1) polymorphisms and susceptibility of childhood asthma and inhaled corticosteroid (ICS) response in children." (PMID 33208131, 2020). "And currently, the studies on the two genes (STIP1 and GLCCI1) and Chinese childhood asthma are still rarely reported." (PMID 33208131, 2020).
clear cell ovarian cancers (1 paper, 2013). "Of the 57 clear cell ovarian cancers which are usually not graded, 40 (70.2%) exhibited a STIP1 histoscore >169." (PMID 23468915, 2013).
colon carcinoma (1 paper, 2020). "In colon cancer, PrPC is known to promote migration by binding to HOP, also known as stress-induced phosphoprotein 1 (STI1)." (PMID 33276687, 2020).
esophageal tumor (1 paper, 2025). "To further investigate the function of STIP1 in vivo, we generated a conditional Stip1‐knockout (Stip1‐cKO) and WT mice model and induced esophageal tumor formation through treatment with the carcinogen 4‐nitroquinoline 1‐oxide (4NQO)." (PMID 41163796, 2025).
hepatitis B virus infection (1 paper, 2024). A viral infection caused by the hepatitis B virus. "We screened 73 ANHC patients and found that age, ALT, AST, GGT, AFP, STIP1, and hepatitis B virus infection were significantly associated with ANHC." (PMID 38780206, 2024). "Univariate analysis revealed statistically significant differences between the 2 groups regarding age, ALT, AST, GGT, AFP, STIP1, and hepatitis B virus infection (P < .05)." (PMID 38780206, 2024). "Age, DCP, STIP1, and hepatitis B virus infection were independent predictors of HCC (P < .05)." (PMID 38780206, 2024). "Additionally, age, STIP1, and hepatitis B virus infection were independent predictors for ANHC patients." (PMID 38780206, 2024).
HIV-1 infection (1 paper, 2012). The type species of lentivirus and the etiologic agent of acquired immunodeficiency syndrome (AIDS). "Since, tropomyosin alpha-4 isoform 1, pyruvate kinase isozymes M1/M2, ER ATPase, and STIP-1 were down-regulated in HIV-1 and HIV-1/HCV infection but not in HCV-infected PBMC, their down-regulation is likely related to the presence of HIV-1 infection." (PMID 22958358, 2012).
Hodgkins lymphoma (1 paper, 2022). A heterogeneous group of malignant lymphoid neoplasms of B-cell origin characterized histologically by the presence of Hodgkin and Reed-Sternberg (HRS) cells in the vast majority of cases. "We have assessed the expression of constitutive and mitochondrial HSP90 and HSP90 co-chaperone STIP1/HOP in two major types of lymphoma- Hodgkin lymphoma and Non-Hodgkin lymphoma." (PMID 35572591, 2022).
lymphoma (1 paper, 2022). A malignant (clonal) proliferation of B- lymphocytes or T- lymphocytes which involves the lymph nodes, bone marrow and/or extranodal sites. "HSP90β and STIP1 were also aberrantly expressed on the surface of bone marrow B cells in lymphoma patients." (PMID 35572591, 2022). "We showed that two lymphomas differ by the expression of intracellular and surface content of HSP90β and STIP1 in peripheral blood and bone marrow lymphocytes." (PMID 35572591, 2022). "We show that constitutive, mitochondrial HSP90s and HSP90 co-chaperone STIP1/HOP are aberrantly expressed in B cells of lymphoma patients." (PMID 35572591, 2022). "We show that B lymphocytes have the highest expression of HSP90β and STIP1 in lymphoma patients." (PMID 35572591, 2022). "Since lymphoma originates from lymphocytes we sought to analyze the expression of HSP90β, TRAP1 and STIP1 co-chaperone in peripheral blood and bone marrow lymphocytes of patients with Hodgkin and Non-Hodgkin lymphomas." (PMID 35572591, 2022). "HSP90β and STIP1 were overexpressed in B lymphocytes, while TRAP1 expression was decreased in T, B, NK and NKT cells of lymphoma patients." (PMID 35572591, 2022).
oral cancer (1 paper, 2022). "We initially evaluated the expression of STIP1 in oral cancer and normal oral mucosa (non-tumor) samples from the TCGA database." (PMID 36713524, 2022).
osteosarcoma (1 paper, 2024). A usually aggressive malignant bone-forming mesenchymal neoplasm, predominantly affecting adolescents and young adults. "Stress-induced phosphoprotein 1 (STIP1) enhances MMP2 and MMP-9 expression in osteosarcoma by activating the PI3K/AKT and ERK1/2 pathways, ultimately promoting CSC metastasis." (PMID 39456967, 2024).
prostate carcinoma (1 paper, 2023). A carcinoma that arises from epithelial cells of the prostate gland. "Ubiquitin proteasome activity is suppressed in enzalutamide resistant prostate cancer cells, and the heat shock protein 70/STIP1 homology and U-box-containing protein 1 (HSP70/STUB1) machinery are involved in androgen receptor (AR) and AR variant protein stabilization." (PMID 36773708, 2023).
psoriasis (1 paper, 2014). An autoimmune condition characterized by red, well-delineated plaques with silvery scales that are usually on the extensor surfaces and scalp. "There are no reports concerning the role of STIP1 in the pathogenesis of psoriasis; however, the present study shows it is possible that STIP1 is a sero-diagnostic marker in patients with psoriasis vulgaris or psoriatic arthritis." (PMID 25010044, 2014). "In this study, a total of 22 psoriasis-associated autoantigens, including moesin, K17, STIP1, and ANXA1, were identified employing 2D-IB with sera from patients with psoriasis." (PMID 25010044, 2014). "Furthermore, serum levels of moesin, keratin 17 (K17), annexin A1 (ANXA1), and stress-induced phophoprotein-1 (STIP1), which were detected as autoantigens, were studied by dot blot analysis with psoriasis patients and healthy controls." (PMID 25010044, 2014). "In this study, we analyzed serum levels of moesin, K17, STIP1, and ANXA1 in psoriasis patients and healthy controls, and measured the stainability of these proteins in psoriasis tissues." (PMID 25010044, 2014). "The STIP1 or moesin, CK17 serum level was not correlated with disease activity of psoriasis patients." (PMID 25010044, 2014).
psoriasis vulgaris (1 paper, 2014). Plaque psoriasis is the most common presentation of psoriasis. "When an optimal cut-off value of 105.8 for STIP1 was applied, the diagnostic sensitivity and specificity for psoriasis vulgaris were 80.6 and 69.2, respectively." (PMID 25010044, 2014). "Our results suggest that moesin and STIP1 may be useful sero-diagnostic markers for psoriasis vulgaris and psoriatic arthritis." (PMID 25010044, 2014). "Two proteins each, moesin and K17 for psoriasis vulgaris, and STIP1 and ANXA1 for psoriatic arthritis, were selected for further experiments, because the expression levels of these proteins were more than twice those in healthy controls." (PMID 25010044, 2014). "Serum STIP1 levels were significantly higher in patients with psoriasis vulgaris or psoriatic arthritis than in healthy controls (P = 0.0025, P = 0.0019, respectively)." (PMID 25010044, 2014). "The levels of moesin and STIP1 were significantly higher in sera from patients with psoriasis vulgaris than in the controls (moesin: P<0.05, STIP1: P<0.005)." (PMID 25010044, 2014). "Relative values of serum STIP1 levels ranged from 75.2 to 286 (median: 152.5), 73.2 to 402.4 (median: 234.1), and 21.0 to 208.2 (median: 86.0) in patients with psoriasis vulgaris, psoriatic arthritis, and healthy controls, respectively." (PMID 25010044, 2014). "STIP1 and K17 levels were significantly higher in sera from patients with psoriatic arthritis than in those with psoriasis vulgaris (P<0.05 each)." (PMID 25010044, 2014). "Serum STIP1 levels of patients with psoriatic arthritis were significantly higher than in patients with psoriasis vulgaris (P = 0.050)." (PMID 25010044, 2014). "The AUC for STIP1 and K17 between patients with psoriatic arthritis and psoriasis vulgaris was 0.69 and 0.72, respectively." (PMID 25010044, 2014). "It is uncertain if there is a direct relationship between STIP1 and the pathogenesis of psoriasis vulgaris or psoriatic arthritis." (PMID 25010044, 2014). "However, the serum STIP1 or moesin, CK17 level was not correlated with PASI score or BSA in patients with psoriasis vulgaris or psoriatic arthritis and DAS28 or BASDAI swollen or tender joint counts, and involved joint counts in patients with psoriatic arthritis." (PMID 25010044, 2014).
psoriatic arthritis (1 paper, 2014). Joint inflammation associated with psoriasis. "When an optimal cut-off value of 195.4 for STIP1 was applied, the diagnostic sensitivity and specificity for psoriatic arthritis were 66.7 and 42.9." (PMID 25010044, 2014). "STIP1 may therefore have an important role in the pathogenesis of psoriatic arthritis through the activation of ERK and JNK." (PMID 25010044, 2014). "Also the serum STIP1 or moesin, CK17, ANXA1 level was not correlated with DAS28 or BASDAI in patients with psoriatic arthritis." (PMID 25010044, 2014).
renal carcinoma (1 paper, 2017). A carcinoma arising from the epithelium of the renal parenchyma or the renal pelvis. "STIP1 was first identified as a renal carcinoma antigen NY-REN-11, a tumor antigen recognized by the humoral immune system." (PMID 28199984, 2017).
serous carcinoma (1 paper, 2013). "Furthermore, in the patients with advanced stages (III and IV) of serous carcinoma and undetermined grade 2–3 (n = 8), all of them had STIP1>169 and 7 of them (87.5%) succumbed to the disease during the follow up of this study." (PMID 23468915, 2013).
Spinocerebellar ataxia, autosomal recessive 16 (1 paper, 2017). "Spinocerebellar ataxia, autosomal recessive 16 (SCAR16) is caused by biallelic mutations in the STIP1 homology and U-box containing protein 1 (STUB1) gene encoding the ubiquitin E3 ligase and dimeric co-chaperone C-terminus of Hsc70-interacting protein (CHIP)." (PMID 28396517, 2017).
viral infections (1 paper, 2024). "Specifically, STIP1, PGAM5, and AKAP8 were over-expressed in VM samples and associated with viral infections." (PMID 38902725, 2024).
tumor (40 papers, 2009 to 2025). "Previous investigations have shown that STIP-1 overexpression is associated with tumor aggression and poor prognosis in various types of cancer." (PMID 33134174, 2020). "Pretreatment STIP1 retained its prognostic value in conventional low-risk subgroups such as single tumors, small tumor size, well differentiation, or complete encapsulation (all P < 0.050)." (PMID 32426271, 2020). "Our analyses further revealed that, even in patients of the same tumor grade, a higher STIP1 level was associated with a poorer clinical outcome." (PMID 23468915, 2013). "Emerging evidence indicates that aberrant STIP1 expression associates with tumor progression." (PMID 41163796, 2025). "Based on these findings, we hypothesized that GOLPH3 associated with STIP1 might regulate hTERT and telomerase activity via c-Myc, and then regulate cyclin D1 to promote the division and proliferation of tumor cells." (PMID 33134174, 2020). "Stratifying by clinicopathologic features, STIP1 was upregulated in ESCCs with greater lymph node involvement, larger tumor size, and more advanced clinical stage." (PMID 41163796, 2025). "Immunohistochemical staining of ESCC tissue microarrays revealed higher STIP1 expression in tumor versus paired normal esophageal tissues." (PMID 41163796, 2025). "Apart from its intracellular role, secreted STIP1 interacts with the cellular prion protein (PrPc) on tumor cell membranes." (PMID 41369326, 2025). "The results demonstrated that STIP1 knockdown significantly attenuated tumor growth in the ESCC CDX models." (PMID 41163796, 2025). "Univariate analysis demonstrated that STIP1 and tumor markers log AFP and DCP were associated factors of HCC, whereas multivariate logistic analysis showed STIP1 and DCP as independent predictors of HCC." (PMID 38780206, 2024). "Although STIP1 is mainly found in the cytoplasm of the cells in most tissues, it has been detected in extracellular vesicles released by both normal and tumor cells." (PMID 36713524, 2022). "STIP1 down-regulation decreased proliferation, migration and invasion of tumor cells, and reduced the number of metastases in the Zebrafish model." (PMID 36713524, 2022). "Immunostaining for STIP1 showed a cytoplasmic pattern, with weak staining restricted to the lower layers of the normal epithelium, whereas tumor cells, in both primary lesions and lymph node metastases, showed variable distribution and intensity." (PMID 36713524, 2022). "Previously, we reported that GOLPH3 interacted with STIP1, which then regulated telomerase activity and promoted tumor progression in pancreatic ductal adenocarcinama." (PMID 35372504, 2022). "Here, we found that STIP1 is overexpressed in OSCCs compared to non-tumor tissues, and its overexpression is an independent prognostic marker for poor outcomes, making it an attractive therapeutic target." (PMID 36713524, 2022). "The impacts of STIP1 silencing on tumor growth and metastasis in vivo were explored with HSC3 clone #1 and SCC9 clones #1 in a zebrafish model." (PMID 36713524, 2022). "In particular, when exposed on the extracellular surface, STIP1 activates autocrine STIP1-ALK2-SMAD1/5 signaling in bone metastatic RCC tumor cells thus promoting cell proliferation, migration, and invasion." (PMID 33418999, 2021). "Consistently, accumulating evidences show that STIP1 is involved in several critical processes that mediate tumor progression including proliferation, migration, and invasion, indicating its necessity in the development of cancer." (PMID 32426271, 2020). "In the last decade, a large number of functions of STIP1 have been reported, which includes the protection of cells in the nervous system, development, cellular maintenance, and tumor proliferation." (PMID 29335007, 2018). "The effective blockade of hrSTIP1-stimulated cell proliferation and migration of the bone-seeking cells elicited by anti-STIP1 antibody further corroborated the role of STIP1 on tumor cells." (PMID 28199984, 2017).
tumor (continued). "The bone-seeking RCC cells have an intrinsic high expression and secretion of STIP1, which promotes tumor cell proliferation and osteoclast maturation." (PMID 28199984, 2017). "The Boyden chamber migration and invasion assay were used to investigate the effects of STIP1 on the RCC tumor cells." (PMID 28199984, 2017). "Our study indicates that STIP1 is such a molecule in mediating the interplay between tumor cells and bone niche in bone metastasis from RCC." (PMID 28199984, 2017). "The growth of tumor cells will further increase the release of osteolytic mediators, STIP1 and others, such as PTHrP." (PMID 28199984, 2017). "The results also demonstrated that increased levels of STIP1 were positively correlated with increased numbers of Ki67-positive tumor cells (the Pearson's correlation coefficient is 0.59)." (PMID 28199984, 2017). "Altogether, these results suggest STIP1 as a clinically relevant factor in mediating RCC tumor development, and motivated us to explore its specific functions in bone metastasis." (PMID 28199984, 2017). "Both intracellular and extracellular STIP1 immuno-reactivities were detected, which further confirmed the secretion of STIP1 into the tumor stromal area." (PMID 28199984, 2017). "Although it is just a correlation analysis between STIP1 and Ki67, these results provided in vivo evidence on STIP1 promoting tumor cell proliferation." (PMID 28199984, 2017). "StIP1 as a crucial chaperone has the possibility to substantial accommodation of cytogenesis in tumor, stress reaction, and cell proliferation and differentiation." (PMID 24455688, 2013). "Collectively, these results indicated that tumor STIP1 histoscoring had a prognostic value in addition to the grading and staging." (PMID 23468915, 2013). "Nevertheless, tumor STIP1 histoscoring clearly exerts a prognostic value in addition to the commonly used, clinical parameters." (PMID 23468915, 2013). "Our results showed increased expression of STIP1 in ductal and highly invasive adenocarcinoma cells in the tumours with weaker positive staining in normal pancreas ducts and acinar cells." (PMID 19216797, 2009). "Specifically, we validated the function of the protein STIP1 in promoting RCC tumor cell proliferation and migration/invasion through the autocrine STIP1-ALK2-SMAD1/5 pathway; and enhancing osteoclast differentiation and proliferation through the paracrine STIP1-PrPc-ERK1/2 pathway." (PMID 38706914, 2024). "Previous research shows that larger nodules may indicate a higher degree of tumor invasiveness, thereby suggesting a potential role for STIP1 in the progression of HCC." (PMID 38780206, 2024). "Whether STIP1 has potential as biomarker for survival and as predictive marker for drug resistance in other tumor types warrants further investigation." (PMID 36839749, 2023). "STIP1 is described as playing a significant role in tumor progression." (PMID 36713524, 2022). "Therefore, the aim of this study was to quantify STIP1 in OSCCs samples compared to non-tumor tissues and evaluate its prognostic value." (PMID 36713524, 2022). "We found that LRRC59 and STIP1 were dysregulated between HNSCC tumor tissues and normal tissues." (PMID 33816266, 2021). "Moreover, we found patients with bigger tumor sizes (diameter over 5 cm) exhibited significantly higher serum STIP1 concentrations in both the resection (P = 0.003) and TACE (P = 0.039) groups." (PMID 32426271, 2020). "Additionally, high pretreatment STIP1 was significantly associated with MVI (P < 0.001) and incomplete tumor encapsulation (P = 0.005)." (PMID 32426271, 2020). "Our results showed that GOLPH3, acting as an oncoprotein, interacted with STIP1 to regulate telomerase activity and promote tumor progression, which might provide a new therapeutic target for PDAC." (PMID 33134174, 2020). "STIP1 promoted tumor metastasis through inducing epithelial-to-mesenchymal transition in GC cells." (PMID 29335007, 2018).